USP15 (ubiquitin specific peptidase 15)
Description:
Hydrolase that removes conjugated ubiquitin from target proteins and regulates various pathways such as the TGF-beta receptor signaling, NF-kappa-B and RNF41/NRDP1-PRKN pathways. Acts as a key regulator of TGF-beta receptor signaling pathway, but the precise mechanism is still unclear: according to a report, acts by promoting deubiquitination of monoubiquitinated R-SMADs (SMAD1, SMAD2 and/or SMAD3), thereby alleviating inhibition of R-SMADs and promoting activation of TGF-beta target genes. According to another reports, regulates the TGF-beta receptor signaling pathway by mediating deubiquitination and stabilization of TGFBR1, leading to an enhanced TGF-beta signal. Able to mediate deubiquitination of monoubiquitinated substrates, 'Lys-27'-, 'Lys-48'- and 'Lys-63'-linked polyubiquitin chains. May also regulate gene expression and/or DNA repair through the deubiquitination of histone H2B. Acts as an inhibitor of mitophagy by counteracting the action of parkin (PRKN): hydrolyzes cleavage of 'Lys-48'- and 'Lys-63'-linked polyubiquitin chains attached by parkin on target proteins such as MFN2, thereby reducing parkin's ability to drive mitophagy. Acts as an associated component of COP9 signalosome complex (CSN) and regulates different pathways via this association: regulates NF-kappa-B by mediating deubiquitination of NFKBIA and deubiquitinates substrates bound to VCP. Involved in endosome organization by mediating deubiquitination of SQSTM1: ubiquitinated SQSTM1 forms a molecular bridge that restrains cognate vesicles in the perinuclear region and its deubiquitination releases target vesicles for fast transport into the cell periphery. Acts as a negative regulator of antifungal immunity by mediating 'Lys-27'-linked deubiquitination of CARD9, thereby inactivating CARD9. (Microbial infection) Protects APC and human papillomavirus type 16 protein E6 against degradation via the ubiquitin proteasome pathway.
Synonyms: KIAA0529; UNPH4; UNPH-2
Tractability: PROTAC: UniProt records ubiquitination sites on it; ubiquitination databases record sites on it; its protein half-life has been measured.
Target class: Enzyme; Hydrolase
Gene: Protein-coding gene on chromosome 12 (62,260,338 to 62,417,431, forward strand). Ensembl gene ENSG00000135655.
Subcellular location: Cytoplasm; Nucleus; Mitochondrion
Subcellular location (Human Protein Atlas): Cytosol; Nuclear bodies; Nucleoplasm
Pathways (Reactome):
Metabolism of proteins: UCH proteinases; Ub-specific processing proteases
Signal Transduction: Downregulation of TGF-beta receptor signaling
Gene Ontology:
Molecular function: cysteine-type deubiquitinase activity; cysteine-type endopeptidase activity; deubiquitinase activity; identical protein binding; K48-linked deubiquitinase activity; protein binding; SMAD binding; transforming growth factor beta receptor binding; ubiquitin-modified histone reader activity; catalytic activity
Biological process: BMP signaling pathway; monoubiquitinated protein deubiquitination; negative regulation of antifungal innate immune response; negative regulation of transforming growth factor beta receptor signaling pathway; positive regulation of RIG-I signaling pathway; protein deubiquitination; protein K27-linked deubiquitination; regulation of RNA metabolic process; transcription elongation-coupled chromatin remodeling; transforming growth factor beta receptor signaling pathway
Cellular component: cytoplasm; cytosol; mitochondrion; nuclear body; nucleoplasm; nucleus
Genetic constraint (gnomAD): Loss-of-function variants: 13 observed, 105.72 expected, observed/expected ratio (o/e) 0.12, 90% interval 0.079 to 0.2. The upper end of that interval is the gene's LOEUF score, 0.2, which puts it in group 1 of 6, group 1 being the genes least tolerant of losing a copy. Missense variants: 728 observed, 1,092.5 expected, observed/expected ratio (o/e) 0.67, 90% interval 0.63 to 0.71. Synonymous variants: 339 observed, 375.28 expected, observed/expected ratio (o/e) 0.9, 90% interval 0.83 to 0.99.
Homologues: Orthologues: macaque USP15 (100% identical), chimpanzee USP15 (99% identical), dog USP15 (99% identical), rat Usp15 (98% identical), mouse Usp15 (98% identical), rabbit USP15 (96% identical), guinea pig USP15 (95% identical), pig USP15 (94% identical), tropical clawed frog usp15 (89% identical). Paralogues in human: USP4 (58% identical), USP11 (44% identical), USP32 (27% identical), USP19 (26% identical), USP6 (24% identical), USP8 (23% identical), USP31 (21% identical), USP9X (21% identical), USP9Y (20% identical), USP24 (20% identical), USP43 (20% identical), USP2 (17% identical), and 59 more.
Diseases named in the same sentence as USP15 in open-access papers:
USP15 is named in the same sentence as 96 diseases in open-access papers, as found by Europe PMC text mining. Sharing a sentence is not in itself a finding about the gene and the disease. The quoted sentences say what the papers report.
glioblastoma (26 papers, 2014 to 2025). The most malignant astrocytic tumor (WHO grade IV). "High levels of amplification of USP15 in individuals with glioblastoma are associated with poor prognosis." (PMID 33946990, 2021). "Expression based prediction of new genomic alterations in glioblastoma identified the de-ubiquitinase Ubiquitin Specific Peptidase 15 (USP15) as potential tumor suppressor gene associated with genomic deletions (11%)." (PMID 29299163, 2017). "The beneficial roles for putative USP15 inhibitors against TGFβ signalling associated pathologies, such as glioblastoma, have been discussed previously." (PMID 24850914, 2014). "The analysis reveals that GINS1 promotes glioblastoma cell proliferation and migration through the mediation of USP15 and TOP2A deubiquitination." (PMID 38301047, 2024). "For instance, USP15 copy number is increased in glioblastoma, breast cancer, and ovarian cancer, but decreased in pancreatic cancer." (PMID 38750011, 2024). "USP15 has been shown to suppress glioblastoma cell growth through stabilizing the E3 ubiquitin protein ligase HECTD1." (PMID 36900163, 2023). "The USP15 gene is highly amplified in glioblastoma and ovarian and breast cancers, and this high expression correlates with enhanced TGF-β activity." (PMID 33946990, 2021). "There is evidence of copy number gains of the USP15 gene in glioblastoma and breast and ovarian cancers, whereas copy number losses have been reported for USP15 in pancreatic cancer." (PMID 33946990, 2021). "In contrast, the depletion of USP15 in a glioblastoma orthotopic mouse model decreases TGF-β activity." (PMID 33946990, 2021). "USP15 regulates inflammation in experimental models and promotes glioblastoma cell proliferation through stabilizing TGF-β signaling." (PMID 33378683, 2020). "USP15 has been shown to stabilize TGF-β receptor I and promote oncogenesis through the activation of TGF-β signaling in glioblastoma, and the USP15 gene is also amplified myeloma and ovarian cancers." (PMID 31952546, 2020). "USP15, thought to be important for the proliferation of glioblastoma cells, deubiquitinates the type I TGFβ receptor via binding to the SMAD7-SMAD-specific E3 ubiquitin ligase 2 (SMURF2) complex." (PMID 32549302, 2020). "Gene expression data available through Oncomine reveal elevated USP15 expression in ovarian serous cystadenoacrcinoma, lobular breast carcinomas, prostate cancer, cervical squamous cell carcinomas, and glioblastomas." (PMID 29593334, 2018). "Copy number alterations for USP15 are reported in glioblastoma, breast, ovarian, and pancreatic cancers." (PMID 29429988, 2018). "USP15 de-ubiquitinated and thereby stabilized HECTD1 in glioblastoma cells, while depletion of USP15 led to decreased HECTD1 protein levels." (PMID 29299163, 2017). "These include ubiquitin-specific peptidase 15 (USP15) in glioblastoma, USP11 in the TGFβ-induced EMT process, and ubiquitin-specific protease 4 (USP4) that participates in the crosstalk between the TGFβ and AKT signaling pathways." (PMID 28758950, 2017). "Exploration of the glioblastoma specific interactome of USP15 indentified HECTD1 as novel top binding partner." (PMID 29299163, 2017). "Taken together, the data provide evidence that USP15 attenuates the canonical WNT pathway mediated by stabilization of HECTD1, supporting a tumor suppressing role of USP15 in a subset of glioblastoma." (PMID 29299163, 2017). "Ectopic expression of USP15 in glioblastoma cell-lines reduced colony formation and growth in soft agar, while overexpression of its functional mutant had the opposite effect." (PMID 29299163, 2017). "Expression of USP15 in glioblastoma cells attenuated WNT-pathway activity, while expression of the functional mutant enhanced the activity." (PMID 29299163, 2017). "The amplification of USP15 gene has been previously identified in glioblastoma, breast cancer and ovarian cancer." (PMID 28245560, 2017).
glioblastoma (continued). "Further, USP15 is upregulated in several malignancies including breast, ovarian, gastric, and bladder cancers, but downregulated in around 25% of pancreatic cancer and 11% of glioblastoma, indicating that USP15 potentially has dual roles in promoting and suppressing tumors." (PMID 39794359, 2025). "Furthermore, the expression of the mesenchymal marker vimentin was notably reduced in USP15‐knockdown cells, which is consistent with prior reports in gastric cancer and glioblastoma." (PMID 40762380, 2025). "Furthermore, USP15 has shown upregulation in various other cancer types, such as glioblastoma, breast cancer, ovarian cancer and gastric cancer, to name a few." (PMID 38656882, 2024). "The antagonistic actions between ubiquitin ligases and DUBs are responsible for protein homeostasis as exemplified that USP13-FBXL14 regulated reversible ubiquitination of c-Myc in glioblastoma stem cells, and USP15-SMURF2 cooperatively modulated TGF-β receptor in glioblastoma." (PMID 35931679, 2022). "Furthermore, USP15 deubiquitinates and stabilizesthe type I TGFβ receptor (TGFβRI) to enhance the TGFβ signaling pathway and promote glioblastoma multiforme cell proliferation and invasion." (PMID 35203682, 2022). "Silencing USP15 also inhibits cell proliferation and invasion in glioblastoma cell lines U87-MG and U251-MG, indicating that USP15 may be a potentially effective treatment target for glioblastoma." (PMID 35203682, 2022). "Moreover, abnormal regulation of the TGFβ signaling pathway by USP15 can lead the occurrence of glioblastoma, breast cancer, and ovarian cancer." (PMID 34177595, 2021). "Importantly, USP15 copy number gains have been reported in glioblastoma, breast, and ovarian cancers and copy number losses identified in pancreatic cancer." (PMID 29429988, 2018). "The USP15 gene is amplified in several cancers including ovarian, glioblastoma, and breast cancer." (PMID 29593334, 2018). "Evaluation of the protein binding network of USP15 by Mass Spectrometry in glioblastoma cells uncovered eight novel interacting proteins, including HECT Domain Containing E3 Ubiquitin Protein Ligase 1 (HECTD1), whose mouse homologue has been associated with an inhibitory effect on the WNT-pathway." (PMID 29299163, 2017). "However, results from some of the studies proved that USP15 possesses oncogenic potential for the promotion of glioblastoma and breast cancer via activation of the TGF-β pathway." (PMID 28245560, 2017). "Additionally, USP15 expression is correlated with paclitaxel sensitivity in ovarian cancer and docetaxel sensitivity in gastric cancer, whereas elevated USP15 expression in human glioblastoma is found to be correlated with a shorter life expectancy." (PMID 33946990, 2021). "Moreover, USP15 plays an important role in glioblastoma by counteracting Parkin-mediated mitophagy." (PMID 34177595, 2021). "However, our data raise the therapeutically interesting opportunity to investigate whether the role for USP15 in preserving self-renewal through genome integrity contributes to its functions in glioblastoma." (PMID 33378683, 2020). "USP15 acted as a DUB in several cancers, such as glioblastoma 51, breast cancer 39 and ovarian cancer." (PMID 40612673, 2025). "A relationship between USP15 and cancer has been proposed by the observation of its stabilization function on the TGF-β receptor in glioblastoma." (PMID 36900163, 2023). "Overexpression of USP15, which correlates with higher TGF-β activity, is mostly found in ovarian cancer, breast cancer, and glioblastomas." (PMID 32549302, 2020). "The overexpression of the USP15 gene results in the dysfunction of the TGF-β pathway, and has been found in several types of cancer, such as glioblastoma, breast, and ovarian cancer." (PMID 28245560, 2017). "In this system, USP15 diminishes canonical Wnt activity by deubiquitinating and stabilizing HECTD1 in a β-catenin-dependent manner, suggesting a tumor-suppressing role of USP15 in glioblastoma." (PMID 33946990, 2021).
glioblastoma (continued). "USP15 can deubiquitinate type I TGF-β receptor (TβR-I) and enhance TGF-β activity; and over-expression of USP15 is closely related to TGF-β activation as well as a poor prognosis for glioblastoma patients." (PMID 30319415, 2018). "In accordance, human glioblastoma display a weak but significant negative correlation between USP15 and AXIN2 expression." (PMID 29299163, 2017).
breast cancer (21 papers, 2014 to 2025). A primary or metastatic malignant neoplasm involving the breast. "Impressively, USP15 has garnered attention in its association with the occurrence and progression of various malignancies, including ovarian cancer, breast cancer, and colorectal cancer." (PMID 38656882, 2024). "The GEPIA, UALCAN, GeneMANIA, and STRING databases were applied to explore the expression of USP15 in breast cancer and associated proteins." (PMID 36213818, 2022). "Next, we performed a meta-analysis of factors related to survival and found that in addition to USP15 expression affecting prognosis in breast cancer patients, age and stage of tumor also had a significant association with prognosis in patients with breast cancer." (PMID 36213818, 2022). "Importantly, USP15 knockdown induced the downregulation of ERα protein via promoting its K48-linked ubiquitination, which is required for proliferative inhibition of breast cancer cells." (PMID 33771975, 2021). "Moreover, USP15 C-terminal is mutated in breast cancer patients, disrupting USP15–BARD1 interaction and resulting in HR defect." (PMID 30874560, 2019). "Interestingly, we identified two mutations of USP15 (M861V and D967H) at the C-terminal D3 region in breast cancer patients." (PMID 30874560, 2019). "USP15 is an important member of the DUBs family 26 and is overexpressed in breast cancer, colorectal cancer, ovarian cancer, and other tumors, and is involved in the genesis and development mechanism of tumors 27-30." (PMID 38577597, 2024). "At the same time, we also found that the expression of USP15 was different in the distribution of breast cancer in different races, including Caucasians (p = 5.12e − 04), African Americans (p = 1.51e − 03), and Asians (p = 5.12e − 04);p = 1.09e − 01)." (PMID 36213818, 2022). "In conclusion, our results suggest that breast cancer metastasis can be blocked by knocking down USP15." (PMID 36213818, 2022). "The results showed that USP15 was highly expressed and then triple expressed in breast cancer patients with metastases." (PMID 36213818, 2022). "The study showed the biological function and accumulation analysis of the USP15 KEGG pathway in breast cancer patients primarily related to cell adhesion and cell metastasis." (PMID 36213818, 2022). "Using Kaplan Meier survival curve analysis software, we subsequently found that high expression of USP15 led to worse survival in breast cancer (p = 0.026)." (PMID 36213818, 2022). "The results showed that the expression of USP15 in different stages of breast cancer was stage 1 (p = 1.04e − 01), stage 2 (p = 4.05e − 03), and stage 3 (p = 4.11e − 03), respectively." (PMID 36213818, 2022). "This requires the development of more specific approaches to tumor metastases; we found that a USP15 target has a significant inhibitory effect on breast cancer metastasis in vitro." (PMID 36213818, 2022). "IL1R2 binds and increases the activity of the ubiquitin-specific protease 15 (USP15) in breast cancer cells." (PMID 35388653, 2022). "The in vitro and in vivo study suggested that overexpression of IL1R2 leads to down-regulation of USP15, and helps in controlling breast cancer malignancy." (PMID 35388653, 2022). "We used Matrigel 3D experiments to investigate further the effect of USP15 on the invasiveness of breast cancer cells." (PMID 36213818, 2022). "Through the TCGA database, we found that USP15 was highly expressed in breast cancer, cholangiocarcinoma, esophageal cancer, head and neck squamous cell carcinoma, renal clear cell carcinoma, gastric adenocarcinoma, and acute myeloid leukemia." (PMID 36213818, 2022). "In this study, we found that USP15 was highly expressed in breast cancer by searching the TCGA databases." (PMID 36213818, 2022). "Then, through the UALCAN and GEPIA database, we found that USP15 in breast cancer significantly reduced the survival rate of premenopausal women (p = 0.011) and triple-negative breast cancer patients (p = 0.038)." (PMID 36213818, 2022).